PCNA (proliferating cell nuclear antigen)
Diseases named in the same sentence as PCNA in open-access papers (continued):
Sharing a sentence is not in itself a finding about the gene and the disease.
cancer (continued). "PCNA and β-catenin levels are increased in animals treated with DMH and treatment with an anti-cancer compound reduces the incidence of ACFs in DMH-induced animals." (PMID 20525330, 2010). "Comparison of the mouse skin pRb/p107/p130 signature mapped to human genes with Signature 5 of mucosal HPV-carcinomas revealed a significant overlap of 7 genes: DHFR, E2F1, LIG1, MCM2, PCNA, RFC4, TYMS and USP1." (PMID 19721808, 2009). "Our study demonstrated that the PCNA inhibitor AOH1996 suppressed HNSCC biological behaviors, impaired cancer stemness, prevented development and metastasis, enhanced the effect of anti-PD1 immunotherapy, promoted cellular DNA damage, and stimulated antitumor immune responses." (PMID 41024256, 2025). "Cancer cells havehigh levels of PCNA expression, which is essential for cellular growth.It was discovered that R9-Peptide with 9 arginine residues (RRRRRRRRR)specifically inhibits the proliferation of cancer cells rather thannonmalignant or normal cells." (PMID 40352490, 2025). "Moreover, BIRC-5, KNTC-1, MCM2, MKI-67, PCNA, and E2F4 genes were downregulated in HCT-116 cancer cell lines, and there was no significant change in the expression of the same genes in HT-29 cancer cell lines." (PMID 40872562, 2025). "In the stromal compartment, phosphorylation of PCNA at Y211 in fibroblasts drives secretion of cytokines such as transforming growth factor beta (TGFβ) and C-X-C motif chemokine ligand 12 (CXCL12), which enhance cancer stemness and invasion potential." (PMID 41170373, 2025). "This fork recovery pathway depends on ubiquitination of PCNA at lysine 164 and is specifically activated in BRCA1- but not BRCA2-deficient cancer cells." (PMID 38943334, 2024). "Melittin has been shown to diminish VEGF and PCNA expression in cancer cells while sparing physiologically normal cells." (PMID 38732255, 2024). "In some studies, PCNA expression was observed in the cancer cell cytoplasm not in normal cells and is related to cell stress." (PMID 39062149, 2024). "These nanoparticles inhibited the proliferation and migration of cancer cells without apparent toxicities in vivo, as demonstrated by the downregulation of proliferating cell nuclear antigen (PCNA) and E-cadherin expression." (PMID 38662225, 2024). "These CHs exert anti-inflammatory, anti-angiogenesis, apoptosis, and cell cycle arrest activities in cancer cells through a wide range of molecular mechanisms such as cyclin-dependent kinase 1 (CDK1), proliferating cell nuclear antigen (PCNA), and nuclear transcription factor kappaB (NFκB)." (PMID 38921023, 2024). "Proliferating cell nuclear antigen (PCNA) is expressed on the cell surface of cancer cells (csPCNA), but not on normal cells." (PMID 37686697, 2023). "Because of the high correlation between CHAF1A and PCNA expression, we hypothesized that CHAF1A and PCNA promote the progression of EC through the synergistic acceleration of cancer cell DNA replication." (PMID 37189802, 2023). "Besides, several proteins were involved in the regulation of DNA damage repair, including PCNA and RAD51, consistent with the significant correlation between dMMR and high TMB in cancer." (PMID 36911742, 2023). "Although a direct interaction between Gal-3 and PCNA or Ki-67 has not been reported in the literature, their roles in promoting cell proliferation and cancer progression suggest potentially interconnected pathways in cancer biology." (PMID 38201234, 2023). "Another study showed that insufficient thermal ablation can facilitate the growth and metastasis of residual hepatic VX2 carcinoma cells owing to the induction of over-expressions of VEGF, proliferating cell nuclear antigen (PCNA) and matrix metalloproteinase-9 (MMP-9)." (PMID 36650834, 2023). "In addition, other cell proliferation markers, such as proliferating cell nuclear antigen (PCNA) and Ki-67, should also be investigated to confirm the protective effects of DRB in the anti-proliferation of cancer cells." (PMID 36360101, 2022).
cancer (continued). "Moreover, both inhibition of PCNA- or REV1-dependent DNA damage tolerance (DDT) have been proposed to chemosensitize cancers to cisplatin, enhancing the efficacy of cancer treatment with platinating agents." (PMID 35819193, 2022). "In addition, FEN1 can modify the epigenetic features in cancer cells by inducing the upregulation of DNA methyltransferase 1 (DNMT1) and DNMT3a and interacting with DNMT3a through proliferating cell nuclear antigen (PCNA)." (PMID 36672839, 2022). "Regarding PTMA and PCNA presence in the cytoplasm and the nucleus of cells in TC samples, we confirm other studies, reporting the increased PTMA expression, together with c-myc, another cell proliferation marker, in several human cancers and cell lines." (PMID 36139050, 2022). "In vivo studies have also confirmed the role of PCLAF in cancer and stem cells independent of PCNA function." (PMID 35210406, 2022). "Low-dose DBP exposure revealed enhanced proliferation and expression of cell cycle genes (including cyclin-D, CCND1, Proliferating Cell Nuclear Antigen, PCNA, and cyclin-dependent kinase 4, CDK4) on prostate (PC3 and 22RV1) (10−6–10−7 M DBP) and breast (BG1) cancer cell lines (10−5–10−8 M DBP)." (PMID 35010832, 2022). "PCNA can be recognized by NKp44 protein (natural cytotoxicity triggering receptor 2; NCR2), leading to inhibition of natural killer (NK) cell’s activity against cancer cells." (PMID 36430528, 2022). "According to TUNEL (apoptosis) findings and PCNA expressions, ASA could exhibit its protective role against the transform from UC (inflammation) to CRC (atypical hyperplasia or cancer) and conduct its apoptosis-inductive effect." (PMID 35946886, 2022). "This means PCNA must be more active in cancer cells than nonmalignant cells in order to maintain genome integrity." (PMID 33498235, 2021). "Cancer-specific changes can also occur in non-oncogenic structural proteins, such as PCNA, which acts as a “hub” in large cellular complexes which are essential for the growth and survival of all cancer cells." (PMID 34831131, 2021). "Additionally, vitamin C and buparlisib co-treatment changed the expression of genes, including PCNA and FILIP1L, which are critical to cancer growth and metastasis." (PMID 33664847, 2021). "Unlike PCNA in normal cells, cancer cells have distinctive features that distinguish them from normal cells." (PMID 33498235, 2021). "Interestingly, our current proteomics data now place MYSM1 in a functional network with PCNA, RFC, HELLS, and MCMBP with potential relevance in hematopoiesis and in cancer progression." (PMID 32466590, 2020). "The abundance of cancer cells may influence the expression of proteins which are highly expressed in the colon tissues (e.g., VEGF and PCNA)." (PMID 32784751, 2020). "Unexpectedly, the IGF1R/PCNA colocalization was absent in most metastatic lesions, neoadjuvantly treated tumors (with poor treatment response) and most cancer cell lines." (PMID 32701997, 2020). "The Colo205 cancer cells showed the most significant decrease of PCNA expression after NP-Pt treatment compared to the non-treated cells (control group)." (PMID 30893818, 2019). "In HCT-15 cells, reduced transcription of cell cycle mediating genes (CCND1, PCNA, CDK2, CDKN1B), and reduced transcription of anti-apoptotic genes (BMI1, BIRC5 and BCL2), support a cancer suppressive and favorable FOXO3/FOXM1 ratio upon combined TNKSi/MEKi treatment." (PMID 30717152, 2019). "The multiple theoretical effects of targeting PCNA with ATX-101 makes it difficult to predict the most prominent downstream effects, and it is likely the combination of multiple effects that results in the increased anti-cancer phenotype observed." (PMID 31921382, 2019).
cancer (continued). "Another intriguing target may be proliferating cell nuclear antigen (PCNA), which is thought to undergo a post-translational modification that is detected only in cancer and cancer precursor cells, as early as the DCIS stage." (PMID 31555644, 2019). "In addition to GTSE1, overexpression of CDC20, PCNA, and MCM has been detected in many types of human cancer." (PMID 32082966, 2019). "Given the addiction of cancer cells to PCNA and cyclin D1, their targeted inhibition has been shown to successfully suppress cancer growth without affecting normal cells." (PMID 30218018, 2018). "In addition, it is well known that PCNA/KI67 and Caspase-3/Bcl-2 are important molecular pathways in cancer cell proliferation and apoptosis." (PMID 28032589, 2017). "Yet, PCNA overexpression is imperative for cancer virulence in broad spectrum of functions; thus, PCNA-mediated immune suppression is probably not the leading drive for its cancer-associated overexpression." (PMID 27765926, 2016). "Only one of the six Rh2E2-treated mice had PCNA-stained LLC-1 cells in the lung tissues, which indicated that Rh2E2 could inhibit the metastasis of LLC-1 cancer cells in vivo." (PMID 26799418, 2016). "We further found that ADSCs could upregulate the mRNA expression of proliferation-related genes in cancer cells, including MKI67 and PCNA." (PMID 25797257, 2015). "Inhibition of proliferating cell nuclear antigen (PCNA) expression indicated that one of the antitumor mechanisms of Kanglaite could be inhibition of karyokinesis and propagation of cancer cells." (PMID 23818930, 2013). "The synergistic effect of EPO and SCF on EPO production observed under normoxic condition in Mz-Cha-2 cells, with a concomitant increase of EPO gene expression, PCNA and CyclinD1, indicates a sensitization to EPO responsiveness as already observed in another cancer cell line." (PMID 23052842, 2013). "Ubiquitination of FANCD2 and PCNA is important for their roles in DNA repair, suggesting that subversion of USP1 in human cancers might impinge on transformation events through alterations of DNA repair pathways." (PMID 21283576, 2011). "Nair and colleagues recently reported an ERα-dependent proliferative effect in which estrogen enhanced PCNA gene expression in cancers of the cervix but not in normal cervix." (PMID 18949048, 2008). "It was found that PCNA labelling in the cancer cells with HCC was stronger than in the hepatocytes with non-malignant diseases." (PMID 17245342, 2007). "Of the proliferative factors analysed (PCNA, cyclin A, cyclin D, the cyclin-dependent kinases cdk2 and cdk4, cell cycle phases) only PCNA and cyclin A (CCNA) exhibited a relationship to sensitivity/resistance and were down-regulated in resistant carcinomas." (PMID 12177790, 2002). "Thesefindings suggest that genetic alterations in PCNA are relatively rareand may not be the primary driver of its high expression in cancers." (PMID 40657100, 2025). "Also,PCNA transcript levels (mRNA) of cancer cell lines in the HPA databasewere examined by incorporating a common approach utilized in otherinvestigations, to bring about a relationshipof the gene as a pan-cancer target." (PMID 40657100, 2025). "PCNA expression is observed in cancer cell nuclei, not in normal cells." (PMID 39062149, 2024). "ELISA analysis of PCNA protein levels in MCF-7 and OVCAR-3 cells confirmed the immunofluorescence staining and showed that the amount of the PCNA protein was significantly increased in cancer cells incubated with 10 nM ES for 48 h compared to all other experimental groups." (PMID 39770406, 2024). "Neither MB-591 nor their combination had an impact on PCNA levels in A2780 cancer cells." (PMID 38675591, 2024).
cancer (continued). "While UHRF2 could not only interact with other Ub/UBL-related proteins that regulate Ub/UBL protein modification, it could also interact with PCNA, DNMT1, HDAC1, and TRDMT1, which participate in DNA replication, cell cycle progression, microRNAs in cancer, etc.." (PMID 38879525, 2024). "Moreover, the expression of CDKN1A and senescence gene FN1 with the lack of expression of PCNA can trigger the G2 arrest or the stress-induced premature senescence (SIPS) found in a previous cancer study." (PMID 38328306, 2023). "Interestingly, exposure to estradiol led to increased PCNA but not Ki67 whereas after DES treatment Ki67 was several folds increased suggesting marked hyperplasia in the cancer sample." (PMID 35676718, 2022). "Besides histological changes, expression of stem cells (OCT-4A, OCT-4, SSEA-1, SCA-1), early differentiation (c-KIT, MVH, Dmrt1a), Sertoli cells (SOX9), cancer stem cells (CD166), proliferation (PCNA, Ki67), global methylation (5mC) and tumor suppresser (PTEN)-specific markers were studied." (PMID 35676718, 2022). "Loss of PCNA-ubiquitination, but not REV1 sensitized mammalian cancer cell lines to cisplatin." (PMID 35819193, 2022). "In comparison to nonmalignant cells, accumulated evidence has shown that PCNA is overexpressed or posttranslationally modified in malignant cells, making it widely used as a biomarker in the diagnosis and prognosis of various cancers." (PMID 33498235, 2021). "Notably, when the endogenous PSP was not disturbed by OA, the exogenous provision of hypoxanthine or inosine did not influence cancer cell proliferation or PCNA expression." (PMID 34703880, 2021). "PCNA is a highly abundant protein, especially in cancer cells Therefore, it is not clear whether p21 levels that can titrate CDKs outside the S phase would ever be sufficient to titrate PCNA within the S phase." (PMID 32481484, 2020). "In MCF-7 cells, AIF upregulated ERα target genes such as proliferating cell nuclear antigen (PCNA), cyclin D1, cyclin E1, cMyc (myelocytomatosis viral oncogene homologue), and liver receptor homologue 1 (LRH-1), and downregulated growth regulation by estrogen in breast cancer 1 (GREB1)." (PMID 31551770, 2019). "Additionally, further investigation revealed that the levels of PCNA, which facilitate to the proliferation of cancer cells, in the cells incubated with SOR while not the PMS is dramatically down-regulated." (PMID 31735093, 2019). "Given the important role of the RAD6/RAD18 (E2/E3) complex in PCNA ubiquitination and polymerase switching from replicative DNA polymerases to damage tolerant TLS polymerases, there is an unmet need to explore if and how such defects can translate into precision cancer medicine." (PMID 29721165, 2018). "Rapidly upregulated PCNA gene expression after hyperthermic chemotherapy with 5-FU was observed in HT-29 cancer cells, whereas no changes were visible after normothermic incubation with the substance (0.5 hours after treatment at 41°C: FD 9.8 and 43°C: FD 19.4) (top)." (PMID 29403306, 2017). "Thus, our data revealed that the global DNA hypomethylation induced by the DNMT1/PCNA/UHRF1 disruption is an oncogenic event of human tumorigenesis, an inducer of epigenetic and genetic signatures frequently observed in several human cancers, and is an initiator of oncogenic events." (PMID 24637615, 2014). "Moreover, a strong correlation was evident between Notch3 and PCNA and between Cyclin G1 and PCNA supporting a role of both Notch3 and Cyclin G1 in cancer progression." (PMID 25431954, 2014).
cancer (continued). "Analogous to the new role of PCNA as an inhibitor of the natural cytotoxicity receptor on natural killer cells, ATX-101 may interfere with the MM cell-BMSC interaction in addition to directly targeting the cancer cells." (PMID 23936203, 2013). "As Rad18 interacts with Rad6 and function as a ubiquitin enzyme to activate PCNA, if these key proteins were involved in cancer, the PRR system will not function and might lead to cancer development." (PMID 19630985, 2009). "Furthermore, certain cell cycle–related proteins, including TOP2A, PCNA, MCM2, MCM4, MCM5, MCM6, and MCM7, have also been reported to facilitate cancer cell proliferation, and the enhanced expression of these cell cycle–related proteins may contribute to uncontrolled ESCC cell proliferation." (PMID 38652547, 2024). "In addition, AKT may be connected with cancer proliferation and apoptosis in epithelial ovarian tumour cells, possibly because of the involvement of AKT in the regulation of downstream signalling molecules, including CyclinD1, Bcl2, PCNA and MMP9." (PMID 37056382, 2023). "However, Shimoni demonstrated that removing the impact of meta-PCNA genes could not effectively reduce the proportion of SSAR gene sets in TCGA cancer types." (PMID 37248269, 2023). "Compared with other PCNA inhibitors, T2AA, PCNA-I1, and AOH1160, AOH1996 selectively kills cancer cells but not normal cells." (PMID 41024256, 2025). "The outcomes showed that in the majority of cancer cases, LIPT2 expression was eminently positively correlated with MKI67, PCNA, BCL2, BAX, and EPCAM, while showing a significant negative correlation with VIM." (PMID 38129565, 2023). "ATX-101 was shown to have a favorable toxicity profile (no myeloid-suppression) and a cancer-stabilizing effect, supporting that ATX-101 mainly targets modified PCNA in stressed cells and does not block normal replication." (PMID 35053455, 2022). "Our studies in mice and in mammalian cells strongly indicate PCNA-ubiquitination is the predominant mode of DDT, and that a genetic ablation of REV1 does not sensitize murine and human cancer cells to various classes of clinically approved DNA damaging agents." (PMID 35819193, 2022). "Accordingly, targeting PCNA with a cell-penetrating peptide containing APIM (APIM-peptide) is shown to mediate changes in PI3K/Akt and MAPK pathways and increase apoptosis in cancer cells also in the absence of exogenous DNA damage." (PMID 35053455, 2022). "The CTGF, IGFBP2, JAG1, and SPARC promoters can provide higher transgene expression in fibroblasts than in cancer cells, but the nonspecific viral promoters CMV, SV40, and the recently studied universal PCNA promoter have the same features." (PMID 33804861, 2021). "The inhibition of PCNA, cyclin D1 and HSPA5 expression by this combination is encouraging as a means to preferentially target cancer cells without affecting normal cells." (PMID 30218018, 2018). "There were no changes in number of Ki-67-positive and PCNA-positive cells between saline- and VACV-injected A431 carcinoma xenografts on days 2 and 4 post-injection, obviously, due to dominating role of the virus replication." (PMID 26771631, 2016). "Immature testicular tissue from untreated cancer patients without any evidence of compromised testicular function (NT group) was used to characterize developmental-related changes in spermatogonial marker expression profiles of MAGEA4, UTF1, PCNA, and 5mC." (PMID 31947706, 2020).